DOCK8 (dedicator of cytokinesis 8)
Diseases named in the same sentence as DOCK8 in open-access papers (continued):
Sharing a sentence is not in itself a finding about the gene and the disease.
actinopathies (6 papers, 2021 to 2025). "Some actinopathies have been studied in this regard and DOCK8 (perhaps more) deficiency has been reported to lead to more T cell death." (PMID 39120629, 2024). "Actinopathies, including DOCK8, WASP and CDC42 deficiencies, are associated with migration defects of various immune cells." (PMID 39120629, 2024). "Recently, we have reported numeric and functional defects in innate lymphoid cells in another actinopathy associated with DOCK8 deficiency." (PMID 39120629, 2024). "A literature review of actine-related IEIs showed that only diseases affecting the CDC42 GTPase pathway, namely WAS and DOCK8, have been reported in large enough numbers to allow a comparative analysis of different actinopathies." (PMID 40860338, 2025). "NK cell function defects have been described for other actinopathies, including DOCK8, WASP, WIP, Arp2/3 and perhaps CARMIL2." (PMID 39120629, 2024). "HSCT is a known treatment for other hematopoietic actinopathies such as WAS and DOCK8 deficiency and would likely rescue HEM1 in all relevant hematopoietic cell lineages." (PMID 35869404, 2022). "Still conversely, we observed dominantly DOCK8 defects and other autosomal recessive diseases as the main genetic defects in this region, indicating the need for the current detailed study on clinical, immunologic and molecular defects of actinopathies using MENA-IEI registry data." (PMID 40860338, 2025). "Mechanisms underlying the allergic immune dysregulation seen in these conditions range from impaired epithelial barrier (SPINK5), to actinopathy (WAS, DOCK8), to altered antigen receptor (CARD11) and cytokine signaling (STAT3)." (PMID 35273610, 2022). "Although we did not observe a clear genotype-phenotype correlation between patients with different types of actinopathies, specific genetic defects mainly from the CDC42 GTPase pathway including WAS and DOCK8 showed higher mortality in the context of severe genetic mutations." (PMID 40860338, 2025).
asthma (6 papers, 2019 to 2025). "The significant differential gene enrichment in CD4+ T cells in pathways such as asthma and inflammatory bowel disease is consistent with some clinical symptoms of DOCK8‐deficient patients, suggesting that the DOCK8 mutation is related to these diseases." (PMID 39329018, 2024). "We identified two potentially novel (SETDB1 and ZNF8) and five previously reported (DM4C, DOCK8, MMP20, MYL7, and ADCY9) genes associated with increased asthma risk." (PMID 37569643, 2023). "Using follow-up bioinformatics analyses, we also confirmed that two novel genes (SETDB1 and ZNF8) and three previously reported genes (DOCK8, MMP20, and ADCY9) are potential asthma-associated genes." (PMID 37569643, 2023). "We also found that IL-21 rescued the function of Bregs in Dock8 KO mice and alleviated inflammatory infiltration in a murine asthma model." (PMID 34867940, 2021). "We found that recombinant murine (rm)IL-21 restored the function of Bregs both in vitro and in Dock8 KO mice, leading to reduced inflammatory cell infiltration of the lungs in a murine asthma model." (PMID 34867940, 2021).
developmental delay (6 papers, 2013 to 2024). "Among them, 33 were reported in CNV studies of developmental delay, and 32 duplications in DOCK8 were reported from other CNV population studies." (PMID 29191242, 2017).
autism (5 papers, 2013 to 2023). Persistent deficits in social interaction and communication and interaction as well as a markedly restricted repertoire of activity and interest as well as repetitive patterns of behavior. "In the Autism Sequencing Consortium cohort, there are patients with de novo loss of function variants associated with the DOCK8 gene in patients with ASD." (PMID 37107578, 2023).
DOCK8 immunodeficiency syndrome (5 papers, 2021 to 2023). "DOCK8 immunodeficiency syndrome (DIDS) caused by DOCK8 deficiency is autosomal recessive inheritance." (PMID 36386145, 2022). "These genes are linked with a range of X-linked and autosomal disorders, e.g., TMLHE (X-linked Autism), CDKL5 (Developmental Encephalopathy), FANCD2 (Fanconi anaemia), FLT4 (congenital heart defects), FTCD (Glutamate formiminotransferase deficiency), and DOCK8 (DOCK8 immunodeficiency syndrome)." (PMID 38033082, 2023). "DOCK8 immunodeficiency syndrome (DIDS) is caused by DOCK8 defects such as mutation or deletion." (PMID 36386145, 2022).
lung carcinoma (5 papers, 2016 to 2023). "The DOCK8 gene and epigenetic inactivation are involved in the development of lung cancer and other cancers by interfering with cell migration, morphology, adhesion, and growth." (PMID 36851274, 2023). "Deletion or down-regulation of DOCK8 was detected in leukemia, lung cancer, renal cell carcinoma, low-grade gliomas and childhood hairy cell astrocytoma." (PMID 36386145, 2022). "Homozygous deletion and reduced expression of DOCK8 were observed in lung cancer." (PMID 26205786, 2016). "DOCK8 was suggested to be involved in the development and/or progression of lung cancer." (PMID 27980454, 2016). "However, to date only 2 papers have reported roles for DOCK8 in lung cancer." (PMID 27980454, 2016).
lymphoma (5 papers, 2020 to 2024). A malignant (clonal) proliferation of B- lymphocytes or T- lymphocytes which involves the lymph nodes, bone marrow and/or extranodal sites. "DOCK8 deficiency has been reported to manifest as young-onset EBV+ and EBV- lymphomas and EBV+ pulmonary lymphomatoid granulomatosis (LYG)." (PMID 35603189, 2022). "Dedicator of cytokinesis-8 (DOCK8) deficiency/hyper IgE syndrome (HIES) leads to impaired NK-cell function and increased predisposition to EBV+ lymphomas." (PMID 35603189, 2022).
molluscum contagiosum (5 papers, 2016 to 2023). A common, benign, usually self-limited viral infection of the skin and occasionally the conjunctivae by a poxvirus (molluscum contagiosum virus). "Autosomal recessive Hyper IgE syndrome due to DOCK8 mutations is associated with generalized molluscum contagiosum, HPV, herpes simplex infections, risk of development of malignancy and /CNS vasculitis." (PMID 36839544, 2023). "DOCK8 defect is an autosomal recessive form of CID characterized clinically by severe cutaneous viral infections such as warts or molluscum contagiosum." (PMID 31572360, 2019).
Sepsis (5 papers, 2019 to 2025). Sepsis is defined as life-threatening organ dysfunction caused by a dysregulated host response to infection. "Animal studies have shown that free heme interferes with DOCK8-mediated Cdc42 activation, inducing extensive actin cytoskeleton changes and strongly suppresses phagocyte functions predisposing to bacterial dissemination and sepsis." (PMID 35386989, 2021). "Thus, partial dominant-negative mutations in DOCK2 (herein) and DOCK8 altering NK cell lytic function may contribute to sHLH development during excess inflammatory states such as sepsis." (PMID 36836791, 2023). "To further elucidate the potential mechanism of DOCK8 in affecting Neutrophil immune function in sepsis, we analyzed the enrichment pathways of DOCK8 through bioinformatics and found that DOCK8 was enriched in the glycolytic signaling pathway." (PMID 37647440, 2023). "In the rescue assay using 2‐DG, we discovered that DOCK8 regulated aerobic glycolysis, thereby inhibiting the immune function of sepsis neutrophils." (PMID 37647440, 2023). "We performed qRT‐PCR to detect the expression of DOCK8 and found that DOCK8 was significantly downregulated in the sepsis cell model (p < .01)." (PMID 37647440, 2023). "Mechanistically, DOCK8 was found to be downregulated in sepsis and sepsis neutrophil, and enriched in the aerobic glycolytic pathway." (PMID 37647440, 2023). "Low expression of DOCK8 facilitated the proliferation, chemotaxis, and phagocytic activity of sepsis cells and promoted the expression of inflammatory factors." (PMID 37647440, 2023). "Expression of DOCK8 in the whole blood of sepsis patients and its enrichment pathways were assayed by bioinformatics." (PMID 37647440, 2023). "Seahorse XF 96 analyses of ECAR showed that knocking down DOCK8 significantly increased the ECAR of sepsis neutrophils." (PMID 37647440, 2023). "We also used CCK‐8 to detect cell viability and found that knocking down DOCK8 significantly promoted the activity of the sepsis cell model, while overexpressing DOCK8 significantly inhibited its activity (p < .01)." (PMID 37647440, 2023). "qRT‐PCR analysis showed that the expression of DOCK8 was significantly lower in the CLP mouse model compared to the sham surgery group (p < .001), indicating a low expression of DOCK8 in sepsis." (PMID 37647440, 2023). "Further detection of the levels of pyruvic acid, lactic acid, and ATP in sepsis cells of each treatment group showed that knocking down DOCK8 significantly increased the levels of pyruvic acid, lactic acid, and ATP." (PMID 37647440, 2023). "In summary, our results demonstrated that DOCK8 was downregulated in sepsis and sepsis neutrophils, suppressing neutrophil immune function in sepsis by regulating aerobic glycolysis." (PMID 37647440, 2023). "In this study, we demonstrated that DOCK8 was downregulated in neutrophils of sepsis cell and CLP mouse models and its depletion suppresses neutrophil immune function in sepsis." (PMID 37647440, 2023). "To investigate the expression of DOCK8 in neutrophils during sepsis, we isolated neutrophils from the blood of sepsis mice and assessed their purity." (PMID 37647440, 2023). "Subsequent experiments further found that DOCK8 inhibited the immune function of neutrophils in sepsis." (PMID 37647440, 2023). "In this study, we first constructed cecal ligation and puncture (CLP) mouse model and a sepsis cell model to analyze the expression of DOCK8 in sepsis and sepsis Neutrophil, and clarified the impact of DOCK8 on sepsis Neutrophil immune function." (PMID 37647440, 2023). "Our findings showed that the expression of DOCK8 was tellingly downregulated in the sepsis cell model after knocking down DOCK8, and significantly upregulated after overexpressing DOCK8 (p < .001)." (PMID 37647440, 2023). "Nevertheless, the precise role of DOCK8 in regulating sepsis neutrophil immune function remains poorly understood." (PMID 37647440, 2023).
Sepsis (continued). "Subsequently, Transwell chemotaxis experiments and phagocytosis experiments were performed to test the immune function, and the results showed that knocking down DOCK8 significantly increased the levels of chemotaxis and phagocytosis in the sepsis cell model." (PMID 37647440, 2023). "This study endeavored to investigate the role of DOCK8 in modulating the immune function triggered by sepsis." (PMID 37647440, 2023). "DOCK8 may inhibit sepsis‐induced neutrophil immune function by regulating aerobic glycolysis and causing excessive inflammation, which helps to explore potential therapeutic targets." (PMID 37647440, 2023). "Bioinformatics analysis of gene expression data from the whole blood of critically ill sepsis patients in the GEO database (GSE134347, which included 83 normal samples and 156 severe sepsis samples) revealed low expression of DOCK8 in sepsis patients (p < 2.2e−16)." (PMID 37647440, 2023). "In conclusion, DOCK8 inhibited the immune function of neutrophils in sepsis via aerobic glycolysis." (PMID 37647440, 2023). "To investigate the potential role of DOCK8 in sepsis, we established a CLP mouse model." (PMID 37647440, 2023). "We also used a Transwell chemotaxis assay and phagocytosis assay to detect the immune function of the sepsis cell model and found that knocking down DOCK8 significantly increased the levels of chemotaxis and phagocytosis, while overexpressing DOCK8 significantly decreased these levels (p < .001)." (PMID 37647440, 2023). "CCK‐8 results illustrated that knocking down DOCK8 notably promoted the activity of neutrophils in sepsis, and treatment with 2‐DG could restore this effect (p < .01)." (PMID 37647440, 2023). "Hence, this study aims to probe into the role of DOCK8 in the pathogenesis of sepsis and its involvement in immune function, with the aim of providing new insights into the disease mechanism." (PMID 37647440, 2023). "In addition, we intend to further explore the upstream transcription factors regulating DOCK8 function to elucidate the specific mechanism by which DOCK8 inhibits sepsis immune function." (PMID 37647440, 2023). "Therefore, we further explored the effect of DOCK8 on the immune function of neutrophils in sepsis, providing new ideas for the treatment of sepsis." (PMID 37647440, 2023). "DOCK8 was downregulated in sepsis blood and activated neutrophils." (PMID 37647440, 2023). "Additionally, qRT‐PCR analysis demonstrated a significant decrease in DOCK8 expression in activated neutrophils, suggesting a reduced expression of DOCK8 in neutrophils during sepsis." (PMID 37647440, 2023). "Therefore, we hypothesized that DOCK8 may regulate aerobic glycolysis to inhibit the immune function of neutrophils in sepsis." (PMID 37647440, 2023). "Patient K1, with a history of endocarditis, vasculitis and sepsis, apparently normal T cell count, showed a high and evident terminal effector CD8+ T cells expansion and later DOCK8 deletion was detected using multiple genetic approaches." (PMID 31849946, 2019). "To probe into the mechanism of neutrophil immune metabolism in sepsis, we knocked down or overexpressed DOCK8 and its negative control in the sepsis cell model, and then measured the transfection efficiency using qRT‐PCR." (PMID 37647440, 2023). "However, there are currently no reports on the regulation of DOCK8 on the immune function of neutrophils in sepsis." (PMID 37647440, 2023).
skin infection (5 papers, 2014 to 2021). An inflammatory process affecting the skin, caused by bacteria, viruses, parasites, or fungi. "Deficiency of dedicator of cytokinesis 8 (DOCK8), a protein involved in regulating the cell actin skeleton, was found to decrease the numbers of CD69+ and CD103+ TRMs surviving in the skin after skin infection." (PMID 34445713, 2021).
antibody deficiency (4 papers, 2019 to 2025). "Moreover, the spectrum of genetic variants identified in our patients—including TNFRSF13B, DOCK8, RAG1, and LRBA—closely resembles the mutational landscape reported in prior studies of CVID and other antibody deficiencies." (PMID 40993545, 2025). "Pathogenic variants in CTLA4, LRBA, TNFRSF13B (TACI), DOCK8, RAG1, PRF1, PIK3CD, IKZF1, and PRKDC have been identified in patients with AICs and PIDs, often associated with other clinical features such as lymphoproliferation, splenomegaly, and immunologic abnormalities such as hypogammaglobulinemia." (PMID 40993545, 2025).
autism spectrum disorder (4 papers, 2019 to 2025). A spectrum of developmental disorders that includes autism, and Asperger syndrome. "DOCK8 is associated with anxiety, opioid dependence, and autism spectrum disorder (ASD)." (PMID 39277688, 2025).
candidiasis (4 papers, 2019 to 2025). Infection with the organism Candida. "Congenital immunodeficiencies with candidiasis, T lymphocyte dysfunction, and IL-17 deficiency have been described in the context of pathogenic variants in genes such as STAT3, CARD9, DOCK8, ACT1, IL-17RC, IL-17RA, and IL-17F—where fluconazole is the first-line treatment." (PMID 40686918, 2025).
dermatitis (4 papers, 2017 to 2023). An inflammatory process affecting the skin. "Moreover, the presentation of dermatitis in patients with DOCK8 deficiency is similar to that typically observed in the classic distribution for AD, making differentiating between these conditions clinically challenging." (PMID 35386989, 2021). "Surprisingly, we found that Dock8−/− AND Tg mice developed severe skin inflammation by the age of 14–15 weeks." (PMID 28067314, 2017). "Although IL-31 has been implicated in pruritus in AD, Dock8−/− OTII Tg mice showed neither skin inflammation nor IgE elevation." (PMID 28067314, 2017). "Here the authors use mice and human samples to show ARNT-independent DOCK8 inhibition of EPAS1 increases transcription of IL-31 in CD4+ T cells, thus driving skin inflammation." (PMID 28067314, 2017). "Dock8−/− AND Tg mice exhibited intense scratching behaviour at 12 and 18 weeks old, indicating that this skin inflammation was pruritic." (PMID 28067314, 2017). "Therefore, it might be possible that CD4+ T cells expressing AND TCR are continuously, albeit weakly, stimulated with self-peptide/I-Ab complexes in vivo, and induce skin inflammation by producing IL-31 only when DOCK8 expression is lacking." (PMID 28067314, 2017). "However, in AND Tg mice lacking both DOCK8 and OSMR (Dock8−/−Osmr−/− AND Tg), scratching bouts per 2 h were reduced to 11.5±9.3, as compared with 200.8±135.8 in Dock8−/−Osmr+/− AND Tg mice, and they did not develop skin inflammation." (PMID 28067314, 2017).
fungal infections (4 papers, 2022 to 2025). "For example, co-mutations in the DOCK8 gene can lead to severe fungal infections." (PMID 40740345, 2025). "However, this patient did not carry any variants in CARD9, IL17RA, L17RC, IL17F, STAT1, DOCK8, MALT1, or TRAF3IP2 genes that can explain the susceptibility to a severe and invasive fungal infection." (PMID 35091979, 2022).
Netherton syndrome (4 papers, 2017 to 2025). Netherton syndrome (NS) is a skin disorder characterized by congenital ichthyosiform erythroderma (CIE), a distinctive hair shaft defect (trichorrhexis invaginata; TI) and atopic manifestations. "Cutaneous viral infections are described in CARD11, LCK, NEMO, GATA2, STK4, DOCK8, and STAT2 deficiencies, STAT1 GOF, Netherton syndrome, WHIM syndrome, and WILD (warts, depressed cell‐mediated immunity, primary lymphedema, and anogenital dysplasia) syndrome." (PMID 37102642, 2023). "Atopic dermatitis (AD) is reported to be correlated with AD‐HIES (job's syndrome), IPEX, Netherton syndrome, PGM3 deficiency, DOCK8 deficiency, STAT3 GOF, Omenn syndrome, activated leukocyte cell adhesion molecule (ALCAM), and hypereosinophilia." (PMID 37102642, 2023).
vasculitis (4 papers, 2018 to 2021). "In DOCK8 deficiency neurologic manifestations include vasculitis, ischemic infarction, hemiplegia, facial paralysis, subarachnoid hemorrhages and progressive multifocal leukoencephalopathy." (PMID 30026765, 2018).
AIDS (3 papers, 2021 to 2025). A syndrome resulting from the acquired deficiency of cellular immunity caused by the human immunodeficiency virus (HIV). "Large condyloma acuminata are frequently reported in patients with primary (e.g., DOCK8 or SPINK5 deficiencies) and secondary (e.g., AIDS, solid organ transplantation) immune defects." (PMID 35562936, 2022).
breast carcinoma (3 papers, 2019 to 2023). "Homozygous deletions of DOCK8 exist in breast cancer and lung cancer." (PMID 31848385, 2019).
chronic mucocutaneous candidiasis (3 papers, 2021 to 2026). "Mutations in genes for IL-17 subunits or their receptors are associated with chronic mucocutaneous candidiasis (CMC), similarly to mutations affecting STAT3 and DOCK8 proteins, resulting in impaired differentiation of IL-17-secreting Th17 cells." (PMID 41481132, 2026). "Chronic mucocutaneous candidiasis (CMC) was significantly more prevalent in HIES compared to SAD, particularly in DOCK8-deficient patients." (PMID 36140582, 2022).
developmental disability (3 papers, 2012 to 2021). Disorders in which there is a delay in development based on that expected for a given age level or stage of development. "Moreover, we have identified a duplication in DOCK8 gene that overlapped with a pathogenic CNV previously reported in individuals with developmental disabilities." (PMID 33503040, 2021). "There were two unrelated patients with mental retardation and developmental disability (MRD2; OMIM #614113) who were disclosed to have a heterozygous disruption of the longest isoform of the DOCK8 gene by either deletion or a translocation of t(X;9)." (PMID 27891178, 2016).